KRAS (KRas proto-oncogene, GTPase)
Diseases named in the same sentence as KRAS in open-access papers (continued):
Sharing a sentence is not in itself a finding about the gene and the disease.
meningioma (3 papers, 2012 to 2014). A generally slow growing tumor attached to the dura mater. "In total, 55 formalin-fixed, paraffin-embedded meningioma samples were subjected to genomic sequencing of EGFR (exons 18–21), KRAS (exon 1), BRAF (exon 15) and PI3K (exons 9, 20)." (PMID 24932282, 2014). "The present study aimed to assess the occurrence of the mutations in the EGFR TK domain and in the selected downstream genes, KRAS, BRAF and PIK3CA, in a relatively large group of meningioma patients." (PMID 24932282, 2014). "Considering inconsistent expression of SOS2/KRAS and JUN/FOS in fibroblastic meningioma, we speculated that activated Ras promoted tumor growth through the PI3K/Akt pathway, but not via ERK-c-Jun/c-Fos pathway." (PMID 23285163, 2012).
mucinous lung adenocarcinomas (3 papers, 2017 to 2023). "Similarly, mice with KRAS mutations and NKX2-1 deletion develop lung tumors that resemble human mucinous lung adenocarcinomas." (PMID 30513627, 2018).
neuropathy (3 papers, 2021 to 2023). A disorder affecting the nervous system that manifests with pain, tingling, numbness, and/or muscle weakness. "In accordance with the importance of the KRAS pathway in several neuropathies, our result showed that dysregulation of the KRAS pathway might be also involved in the pathogenesis of ALS based on genetic features." (PMID 33809961, 2021).
neutropenia (3 papers, 2018 to 2022). A decrease in the number of neutrophils found in the blood. "The augmented momelotinib exposure noted in this study may partly account for the higher rates of neutropenia observed compared with the combination study of momelotinib and trametinib in KRAS-mutated NSCLC." (PMID 34773474, 2022). "There was no neutropenia event with momelotinib dosed up to 150 mg BID as reported in combination with MEK1/2 inhibitor trametinib in patients with KRAS-mutated NSCLC." (PMID 34773474, 2022). "In a phase II trial evaluating the FOLFOXIRI + cetuximab regimen on 13 wild-type KRAS exon 2 codon 12 mCRC patients, the RR, median PFS, and median OS were 70% and 10.2 and 30.3 months, respectively, although there were high rates of Grade ≥ 3 neutropenia (23%), diarrhea (53%), and stomatitis (10%)." (PMID 29464396, 2018).
nevus (3 papers, 2021 to 2025). Nevus (or naevus, plural nevi or naevi, from nævus, Latin for "birthmark") is the medical term for sharply circumscribed[1] and chronic lesions of the skin or mucosa. "​​Nevus sebaceous is considered to be caused by postzygotic mosaic mutations in the HRAS or KRAS genes, leading to somatic mosaicism and activation of pathways such as MAPK and PI3K-AKT, promoting cellular proliferation." (PMID 41322847, 2025).
odontogenic tumors (3 papers, 2020 to 2025). "Instead, AOTs frequently harbor KRAS mutations, further supporting their unique molecular profile among benign odontogenic tumors." (PMID 41364259, 2025). "We detected recurrent KRAS p.G12V (n = 15/38) or p.G12R mutations (n = 12/38) in 27 out of 38 adenomatoid odontogenic tumors (71%) regardless of the age of the patient, tumor size, tumor location, follicular or extrafollicular variants, and fibrous capsule thickness." (PMID 35048058, 2021).
ovarian teratoma (3 papers, 2012 to 2021). A non-seminomatous germ cell tumor arising from the ovary. "In our study, we describe an unusual case of KRAS mutation-harboring FV-PTC in a patient with bilateral ovarian teratoma." (PMID 22682753, 2012).
overgrowth syndrome (3 papers, 2020 to 2022). A group of syndromes caused by genetic birth defects that may lead to the development of malignancies. "Using our tissue analysis workflow including 17 genes associated with overgrowth syndrome, also no pathogenic variant could be identified, whereas LB analysis identified KRAS (NM_004985.5) c.35G>A p.(Gly12Asp) in plasma with a measured VAF of 1.01%." (PMID 36636551, 2022). "Taken together, detection of KRAS c.35G>A, p.(Gly12Asp) variant using LB that could not be identified with the tissue workflow, molecularly explained the clinically diagnosed overgrowth syndrome in our patient, hereby providing personalized treatment options including MEK inhibitors." (PMID 36636551, 2022).
papillary adenoma (3 papers, 2013 to 2015). An adenoma characterized by the presence of papillary epithelial patterns. "Morphologically, the keratin-deficient tumors were typical papillary adenomas and adenocarcinomas indistinguishable from the neighboring keratin positive tumors on the same slide or from KRAS-induced lung tumors from keratin wild type animals." (PMID 23536778, 2013).
peritoneal (3 papers, 2016 to 2025). "Secondly, in the present study, we did not assess the therapeutic effects of anti-inflammatory drugs or anti-angiogenic drugs on KRAS- or c-MYC-induced peritonitis." (PMID 27483433, 2016). "In the BBP group, 33 patients (89.2%) were PS ≤1, 11 patients (32.4%) had KRAS/RAS wildtype, and 8 patients (21.6%) had peritoneal metastasis." (PMID 34715820, 2021).
plasma cell leukemia (3 papers, 2021 to 2024). An aggressive plasma cell neoplasm characterized by the presence of neoplastic plasma cells in the peripheral blood. "According to published data, mutations of RAS family genes (KRAS, NRAS, BRAF) occur in less than 10% in MGUS, in 50% of symptomatic MM, and in more than 70% of cases of plasma-cell leukemia, which indicates activation of this pathway in the progression of the disease." (PMID 36833278, 2023).
pleura (3 papers, 2017 to 2023). "Here we use immunocompetent mouse models of MPE to show that mutant KRAS determines the responsiveness of pleural tumor cells to host-delivered interleukin (IL)-1β signals by directly regulating IL-1 receptor 1 (IL1R1) expression." (PMID 29445180, 2018). "This was in accord with the equal total mass of pleural tumors per mouse observed across pleural-injected KRAS-mutant and wild-type tumour cells." (PMID 28508873, 2017). "Taken together, these results indicated that KRAS-mutant pleural tumours induce the sequential recruitment of CD11b+Gr1+ cells from the bone marrow to the spleen and into the pleural cavity." (PMID 28508873, 2017). "However, a unifying mechanism linking KRAS mutations with oncogenic NF-κB activation and MPE competence of pleural tumor cells was missing." (PMID 29445180, 2018). "In addition to triggering a myeloid inflammatory response, KRAS-mutant pleural tumours and MPEs showed enhanced angiogenic and vasoactive potential in several in vivo assay systems compared with KRAS-wild-type tumours." (PMID 28508873, 2017). "Furthermore, that during MPE formation, bone marrow-borne, splenic CD11b+Gr1+ cells are conditioned by solute mediators secreted by KRAS-mutant pleural tumours (possibly CCL2) and functionally contribute to MPE development." (PMID 28508873, 2017). "Collectively, these results suggested that mutant KRAS-driven MPE is associated with induction of an inflammatory, angiogenic, and vasoactive response in the pleural space, but not necessarily with enhanced pleural tumour growth." (PMID 28508873, 2017).
primary immunodeficiency (3 papers, 2022 to 2025). "For instance, Ras-associated autoimmune lymphoproliferative disorder (RALD) is a sporadic primary immunodeficiency disease caused by somatic mutations in the KRAS and NRAS genes, which result in ALPS-like manifestations." (PMID 40364944, 2025). "Enrichments were seen in the “primary immunodeficiency pathway” and “KRAS signaling pathway”." (PMID 35847920, 2022).
prostate adenocarcinoma (3 papers, 2017 to 2026). "Similarly, KRAS, a frequently altered oncogene in prostate adenocarcinoma, represents another potential regulatory node influenced by miRNA-mediated mechanisms." (PMID 41595499, 2026).
prostate tumors (3 papers, 2017 to 2022). "Gene expression quantification of selected oncogenes and tumor suppressor genes, involved in this pathway showed that KRAS and BCL2 were consistently upregulated in prostate tumor specimen, whereas PTEN was consistently downregulated." (PMID 29268752, 2017).
rheumatoid arthritis (3 papers, 2018 to 2021). A chronic, systemic autoimmune disorder characterized by inflammation in the synovial membranes and articular surfaces. "Moreover, hyperactive KRAS signaling often occurs in common immunological and inflammatory disorders, such as rheumatoid arthritis (RA) and diabetes." (PMID 29440631, 2018).
Rosai-Dorfman disease (3 papers, 2023 to 2025). "Recent research has revealed that the development of Rosai-Dorfman disease (RDD) may be closely linked to specific genetic mutations, such as BRAF, KRAS, and NRAS involving in the abnormal activation of the MAPK/ERK signaling pathway." (PMID 40018414, 2025).
salivary gland cancer (3 papers, 2015 to 2023). A primary or metastatic malignant neoplasm that affects the major or minor salivary glands. "To identify the genetic mutation that contributed to the pathogenesis of SDC, one of the most aggressive subtypes of salivary gland cancers, we investigated 18 SDC biospecimens to search for either somatic KRas or EGFR mutation." (PMID 26289340, 2015).
Sarcomatoid carcinomas of the lung (3 papers, 2015 to 2025). "We further found that lung sarcomatoid carcinoma had a high frequency (37.5%) of KRAS mutations." (PMID 26486077, 2015).
serrated polyposis (3 papers, 2011 to 2020). "The balance of CRC (BRAF wild-type) in serrated polyposis either demonstrates somatic KRAS mutation at a rate of approximately 19% which is half that of the population or is oncogene mutation null." (PMID 21660283, 2011). "Small numbers of serrated polyps as well as CRCs with somatic KRAS mutation are also observed in serrated polyposis patients." (PMID 21660283, 2011). "However, rare cases of serrated polyposis are reported where KRAS mutations predominate, and current evidence suggests that, in at least some of these patients, biallelic germline mutation of MUTYH may be responsible." (PMID 21660283, 2011). "Additionally, assessing for CIN in serrated or hyperplastic polyposis syndrome (SPS, HPS) samples could shed light onto the pathway of neoplastic progression for serrated polyposis syndrome and HPS and KRAS mutations have been implicated in both." (PMID 32257372, 2020).
spindle cell sarcoma (3 papers, 2017 to 2024). A malignant mesenchymal neoplasm composed of spindle-shaped cells. "Among mesenchymal tumors of the pancreas, a potential diagnosis is undifferentiated spindle cell sarcoma, which is less likely given the presence of a KRAS mutation, which is uncommon in pancreatic sarcoma." (PMID 39594178, 2024). "Here, we describe a patient with a spindle cell sarcoma presenting a p.G12V KRAS mutation." (PMID 33130216, 2021). "We report an unconfirmed partial response and prolonged clinical benefit from CCT3833 in one of these patients, diagnosed with a KRAS-mutant spindle cell sarcoma." (PMID 33130216, 2021). "The patient in our study had an unusually aggressive spindle-cell sarcoma, supporting KRAS not only as biomarker, but as a driving gene of the disease progression." (PMID 28061772, 2017). "Based on these preclinical data and the phase I clinical unconfirmed response in a patient with KRAS-mutant spindle cell sarcoma, CCT3833 requires further evaluation in patients with other KRAS-mutant cancers." (PMID 33130216, 2021). "Herein, we report that the new inhibitor, CCT3833, mediated an unconfirmed partial response in a patient with aggressive KRAS-mutant spindle cell sarcoma who was not eligible for surgery or chemotherapy, and who did not respond to the multikinase inhibitor pazopanib." (PMID 33130216, 2021).
uterine serous carcinoma (3 papers, 2017 to 2021).
uterine tumor (3 papers, 2019 to 2022).
Venous malformation (3 papers, 2021 to 2025). A vascular malformation resulting from a developmental error of venous tissue composed of dysmorphic channels lined by flattened endothelium and exhibiting slow turnover. "We found the same GLMN variant c.108C > A (p.(Cys36*)), both in a patient with an AVM and in a patient with venous malformations in association with a somatic KRAS variant c.35G > A (p.(Gly12Asp)) and a somatic FGFR3 CNV, respectively." (PMID 35807022, 2022).
acute monoblastic leukemia (2 papers, 2012 to 2023). "In contrast, LZTR1 deficiency increased RIT1, KRAS, MRAS, and NRAS expression in fetal liver and acute monocytic leukemia cells." (PMID 37626065, 2023).
adenomatoid odontogenic tumor (2 papers, 2021 to 2022). A benign, slow growing neoplasm arising from tooth-forming tissues. "Importantly, KRAS p.G12V or p.G12R mutations have been reported in ~70% of adenomatoid odontogenic tumors, an encapsulated and indolent epithelial odontogenic tumor." (PMID 35048058, 2021).
adenomatous colonic polyps (2 papers, 2022 to 2025). "APC mutations were found in 75% of sporadic colonic adenomatous polyps and carcinomas that we examined, while KRAS mutations were found in 25% of cases." (PMID 41488735, 2025).
anaplastic astrocytoma (2 papers, 2021 to 2024). "In anaplastic astrocytoma, RAS mutations typically involve alterations in the HRAS, KRAS, or NRAS genes." (PMID 39459475, 2024).
anaplastic large cell lymphoma (2 papers, 2019). Anaplastic large cell lymphoma (ALCL) is a rare and aggressive peripheral T-cell non-Hodgkin lymphoma, belonging to the group of CD30-positive lymphoproliferative disorders, which affects lymph nodes and extranodal sites. "STAT3 suppression decreases PD-L1 expression in ALK-positive anaplastic large cell lymphoma (ALCL) and KRAS-mutant non-small cell lung cancer (NSCLC) cells." (PMID 31835799, 2019).
appendiceal neoplasm (2 papers, 2017 to 2021). A benign or malignant neoplasm involving the appendix. "PMP, a related malignancy that arises from appendiceal neoplasms is also characterized by the production of excessive mucinous ascites (leading to bowel obstruction in advanced disease, the primary cause of patient mortality) and a high rate of KRAS mutations." (PMID 28640835, 2017).
ascending colon cancer (2 papers, 2021 to 2023). A malignant neoplasm involving the ascending colon. "A 63-year-old female patient was diagnosed as having a KRAS-mutant ascending colon cancer with distant metastasis (cT4aN1M1)." (PMID 34347396, 2021).
astrocytic tumor (2 papers, 2021 to 2023). A glial tumor of the brain or spinal cord showing astrocytic differentiation. "KRAS and PTEN mutations maintain cell growth by activating AMPK in astrocytic tumors." (PMID 33331115, 2021).
atrophic gastritis (2 papers, 2023 to 2025). "D1, collected from the patient during a period of gastric atrophy, robustly colonized both KRAS− and KRAS+ mice, and titers were greater in KRAS+ stomachs than KRAS− stomachs." (PMID 36598261, 2023).
bowel obstruction (2 papers, 2013 to 2017). "While the patient’s resected tumors from both 2004 and 2009 showed the presence of wild-type KRAS, and the administration of cetuximab for 2 years and 4 months proved effective, the resected seeding tissue from his intestinal obstruction was found to have a KRAS mutation." (PMID 24304820, 2013).
brain ischemia (2 papers, 2020 to 2024). Diminished or absent blood supply to the brain caused by obstruction (thrombosis or embolism) of an artery resulting in neurologic damage. "Indeed, ERK activation is causally linked to inflammation in many instances: oncogenic KRAS G12V drives inflammation in mice and human leukemic monocytes, and ERK inhibition blocks inflammation due to cerebral ischemia in mice." (PMID 39403923, 2024).
cecal cancers (2 papers, 2014 to 2024). "In our current study, cecal cancers appeared to be significantly associated with overall KRAS mutation status, and this trend was evident across all four mutated codons." (PMID 24885062, 2014). "Therefore, cecal cancers appeared to represent a unique subtype, characterized by a high frequency of KRAS mutation." (PMID 38402201, 2024). "The association between cecal cancers and KRAS mutations is intriguing." (PMID 24885062, 2014). "Further studies are needed to elucidate why KRAS mutations, irrespective of mutated codon, are particularly common in cecal cancers." (PMID 24885062, 2014).
celiac disease (2 papers, 2023 to 2025). An autoimmune genetic disorder with an unknown pattern of inheritance that primarily affects the digestive tract. "Two (13%) cases, one of which was associated with celiac disease and the other one with Crohn disease, harbored KRAS amplifications." (PMID 36812376, 2023).
cholestasis (2 papers, 2002 to 2024). Impairment of the bile flow caused by obstruction within the liver, or outside the liver in the bile duct system. "Patients with cholestasis were observed with slightly more frequent KRAS mutation, higher T stage and less primary tumor resection, indicating a more malignant biological behavior of the tumor, which further contributed to a shorter survival." (PMID 38951890, 2024).
colorectal serrated adenocarcinoma (2 papers, 2011 to 2022). A rare, invasive colorectal adenocarcinoma characterized by the presence of a malignant infiltrate with serrated glandular architecture. "Interestingly, KRAS mutations happen to be more common in colorectal serrated adenocarcinoma that involves the NF-kB pathway and the secretion of IL-8 which may account for the association of the higher abundance of Faecalibacterium in KRAS mutated CRC patients." (PMID 35727391, 2022).
Crohn disease (2 papers, 2021 to 2023). A gastrointestinal disorder characterized by chronic inflammation involving all layers of the intestinal wall, noncaseating granulomas affecting the intestinal wall and regional lymph nodes, and transmural fibrosis. "It should be added that Yaeger et al51 found higher rates of KRAS (33%) and APC (39%) mutations in intestinal, mainly colorectal, carcinomas associated with Crohn disease in comparison with SB-PCCs related to Crohn disease of our study (0% and 8%, respectively)." (PMID 36812376, 2023). "However, at least some molecular findings found in our SB-PCC cases, such as the lack of KRAS and PIK3CA point mutations, are likely histotype dependent, as they are observed in SB-PCCs with or without Crohn disease and are not a feature of Crohn disease–associated SBAs in general." (PMID 36812376, 2023).
Down syndrome (2 papers, 2017 to 2021). "In the current study, we also observed co-occurrence of JAK2 and KRAS lesions in non-Down syndrome BCP-ALL cells." (PMID 29163799, 2017). "Interestingly, a new study revealed that the activation of KRAS wild-type alone is sufficient to induce oncogenic KRAS properties in cases of Down Syndrome (DS)-ALL." (PMID 33801965, 2021).
duodenal cancer (2 papers, 2012 to 2024). "The KRAS G12D mutation was found in FFPE tumor, but not in plasma from a patient with duodenal cancer." (PMID 23144797, 2012).